MIR125B2 (microRNA 125b-2)
Synonyms: hsa-mir-125b-2; MIRN125B2; mir-125b-2
Gene: MicroRNA gene on chromosome 21 (16,590,237 to 16,590,325, forward strand). Ensembl gene ENSG00000207863.
Gene Ontology:
Biological process: miRNA-mediated post-transcriptional gene silencing
Cellular component: RISC complex
Homologues: Orthologues: chimpanzee ptr-mir-125b-2 (100% identical), dog MIR125B2 (100% identical), macaque mml-mir-125b-2 (100% identical), pig ssc-mir-125b-2 (100% identical), rabbit MIR125B2 (100% identical), tropical clawed frog xtr-mir-125b-2 (83% identical), guinea pig MIR125B2 (75% identical), zebrafish mir125a-2 (60% identical), zebrafish mir125a-1 (57% identical). Paralogues in human: MIR125B1 (64% identical), MIR125A (61% identical), MIR99A (48% identical), MIR100 (45% identical), MIR10B (44% identical), MIR10A (40% identical), MIR99B (39% identical).
Diseases named in the same sentence as MIR125B2 in open-access papers:
MIR125B2 is named in the same sentence as 1 disease in open-access papers, as found by Europe PMC text mining. Sharing a sentence is not in itself a finding about the gene and the disease. The quoted sentences say what the papers report.
tumor (1 paper, 2023). "Analysis showed MIR125B2 was paternally, but not maternally, expressed in the temporal cortex of normal and tumor tissue of a 17-year-old female." (PMID 36918719, 2023).